CD80 (CD80 molecule)
Diseases named in the same sentence as CD80 in open-access papers (continued):
Sharing a sentence is not in itself a finding about the gene and the disease.
thyroid cancer (4 papers, 2018 to 2025). "Significant moderate to strong positive correlations were recorded between PD-L1 and PD-L2, PD-L1 and CD80, and PD-L2 and CD86 in thyroid cancer tissues." (PMID 30123257, 2018). "In our findings, the correlation analysis evidenced a moderate significant covariation between CD80 and CD86 mRNA levels in thyroid cancer tissues." (PMID 30123257, 2018). "Moreover, few studies examined the CTLA-4 ligand (CD80 and CD86) gene expression at the protein level in thyroid cancer cell lines and tissues, including PTC and ATC tissues." (PMID 30123257, 2018). "In thyroid cancer, Angell and colleagues demonstrated that there was a tendency for BRAF mutant tumors to have higher CD163 expression than CD80, but they also reported that this varied significantly between patients, with some having higher CD80 and others CD163." (PMID 37686663, 2023).
type 2 diabetes (4 papers, 2011 to 2023). "Here we report that adults with type 2 diabetes have significantly up-regulated surface expression of CD40 and CD80 with a lag of 2 and 3 days and significantly elevated CD86, HLA-DR, and CD23 expression at a lag of 4 days on circulating monocytes." (PMID 21169129, 2011).
abortion (3 papers, 2014 to 2023). the ending of pregnancy by removing a fetus or embryo before it can survive outside the uterus. "A higher M1/M2 ratio of dMφs was demonstrated in spontaneous abortion, which manifested a higher expression of M1-associated markers (CD86, CD80, and IL-1β) and lower expression of M2-associated markers (CD209, CD206, IL-10, and TGF-β1." (PMID 37033974, 2023). "Among the costimulatory molecules on B cells, SGS downregulated the expression of the CD80 antigen and consequently inhibited maternal rejection of fetuses in abortion-prone mice." (PMID 34298914, 2021). "In the context of pregnancy, the blockade of CD80 and CD86 molecules in early stages of gestation abortion-prone mice (CBA/JxDBA/2) increased production of Th2 cytokines and frequency of Treg cells and decreased the fetal resorption." (PMID 24771983, 2014). "Furthermore, the systemic inhibition of CD80 and CD86 at the implantation period of pregnancy inhibited the rejection of fetuses in abortion-prone mice." (PMID 34298914, 2021).
AIDS (3 papers, 2015 to 2022). A syndrome resulting from the acquired deficiency of cellular immunity caused by the human immunodeficiency virus (HIV). "Compared with normal neutrophils, LDNs in patients with acquired immunodeficiency syndrome expressed increased levels of CD15, CD33, CD66b, and decreased levels of CD62L, CD80, CD114, and CXCR417." (PMID 35027618, 2022). "Therefore, in order to characterize gut-associated pDCs in HIV/AIDS cases and controls, we probed the respective duodenum biopsies with fluorescently labeled anti-CD303, anti-CD123, anti-CD4, and anti-CD80 monoclonal antibodies." (PMID 26441989, 2015). "In addition to CD14, CD33+ macrophages in AIDS patients co-expressed the Fc receptor γ (CD16) and T cell the co-stimulatory molecules CD80 and CD86." (PMID 26475133, 2015).
allergic asthma (3 papers, 2025 to 2026). A asthma with a basis in a pathological type I hypersensitivity reaction. "As CD80 is associated with inflammatory eosinophil phenotype, we assessed the expression of CD11c, which characterizes pro-inflammatory eosinophils in allergic asthma inflammation and is expressed by intestinal tissue murine eosinophils." (PMID 40831561, 2025). "Our findings showed that IgE-hFcεRI-dependent upregulation of co-stimulatory CD80, CD86, and CD40 on hFcεRI eosinophils would be consonant with a recent study of 32 allergic asthma subjects who had clinically beneficial responses over 16 weeks of treatment with the anti-IgE mAb, omalizumab." (PMID 39996772, 2025).
B-cell neoplasm (3 papers, 2013 to 2024). A group of heterogeneous lymphoid tumors generally expressing one or more B-cell antigens or representing malignant transformations of B-lymphocytes. "The effective communication between two subsets of co-stimulatory molecules of neoplastic B cells, CD80 (B7.1) and CD86 (B7.2), and the CD28 or cytotoxic T-lymphocyte–associated antigen 4 (CTLA-4) of T cells, is thought to play important roles in the tumorigenesis of B cell neoplasms." (PMID 30999581, 2019). "Unlike dogs, CD80 is expressed on human peripheral blood B cells and memory and germinal center B cells, which would explain the positive reactions in B cell neoplasms." (PMID 39224452, 2024).
cardiomyopathy (3 papers, 2018 to 2022). A disease of the heart muscle or myocardium proper. "Furthermore, only CD86 was associated with Treg cells, while CD80 showed a negative correlation with these regulatory cells only in the groups without cardiomyopathy (NI and IND)." (PMID 29599775, 2018). "We have previously demonstrated an association between CD86 receptor expressed in non-classical monocytes with Treg lymphocytes, while a negative correlation with CD80 by total monocytes and these regulatory cells was found in patients without cardiomyopathy (NI and IND), but not in CARD group." (PMID 35665256, 2022).
Crohn disease (3 papers, 2012 to 2020). A gastrointestinal disorder characterized by chronic inflammation involving all layers of the intestinal wall, noncaseating granulomas affecting the intestinal wall and regional lymph nodes, and transmural fibrosis. "CD80 and CD86 were induced by most probiotic strains in ulcerative colitis (UC) patients whereas only B. bifidum induced CD80 and CD86 expression in Crohn’s disease (CD) patients." (PMID 32872480, 2020). "Tol-DCs generated from Crohn’s disease patients showed a statistically significant impairment in the upregulation of CD80, CD83 and HLA-DR compared to iDCs, with no CD86 modification." (PMID 23300676, 2012).
dengue (3 papers, 2013 to 2015). "In our previous study, several genes involved in the TLR6 pathway have been found to be significantly up-regulated during dengue virus infection in K562 cells on day 3 post-infection which include TLR6, IL-6, TNF-α and CD80." (PMID 26226614, 2015). "In this study we examined the expression level of TLR2, 3, 4 and 9 and of the co-stimulatory molecules CD80 and CD86 in dengue patients experiencing distinct disease manifestations." (PMID 23469297, 2013). "Furthermore, the expression of CD80 and CD86 was altered in mDCs and CD86 in pDCs of severe dengue cases." (PMID 23469297, 2013). "In addition, expression of CD80 and CD86 was altered in DCs of severe dengue cases." (PMID 23469297, 2013).
diffuse large B-cell lymphoma (3 papers, 2020 to 2025). "We identify an upregulation of CD80 and/or CD86 in tumor tissue of (r/r) diffuse large B cell lymphoma (DLBCL) patients treated with tisagenlecleucel." (PMID 38340727, 2024).
Fabry disease (3 papers, 2016 to 2023). Fabry disease (FD) is a progressive, inherited, multisystemic lysosomal storage disease characterized by specific neurological, cutaneous, renal, cardiovascular, cochleo-vestibular and cerebrovascular manifestations. "We measured the urinary excretion of CD80, podocyturia and proteinuria in controls and in subjects with Fabry disease either untreated or on enzyme replacement therapy (ERT)." (PMID 27733175, 2016). "CD80 mRNA expression in response to lyso-Gb3, a bioactive glycolipid accumulated in Fabry disease, was studied in cultured human podocytes." (PMID 27733175, 2016). "In this study, we explored the urinary excretion of CD80 in patients with Fabry disease and the potential drivers of CD80 expression." (PMID 27733175, 2016). "Since uCD80 was increased in the urine of Fabry patients, we next explored the expression of CD80 in human Fabry disease tissue." (PMID 27733175, 2016). "This suggests that podocyturia and urinary CD80 expression may provide information into early and continuing kidney injury in Fabry disease." (PMID 27733175, 2016). "Since uCD80 was increased early in Fabry nephropathy, even in the group of patients with better preserved eGFR and lower albuminuria, we explored whether glycolipids accumulated in Fabry disease may increase CD80 expression in kidney cells." (PMID 27733175, 2016). "In Fabry disease, kidney cell CD80 expression may be driven by accumulated glycolipids, as shown in our cell culture experiments, and thus, it may provide information about continuing kidney injury by glycolipids despite ERT." (PMID 27733175, 2016). "In Fabry disease podocyturia and urinary excretion of CD80 rise early in the disease process, even in patients with normal renal function." (PMID 27733175, 2016).
follicular lymphoma (3 papers, 2018 to 2024). Follicular lymphoma is a form of non-Hodgkin lymphoma characterized by a proliferation of B cells whose nodular structure of follicular architecture is preserved. "Follicular lymphoma or mantle cell lymphoma also showed an increased expression of CD80 and/or CD86 in response to TLR9 agonist." (PMID 29805758, 2018). "For example, upregulation of CD80/CD86 and other costimulatory and adhesion molecules leads to increased APC activity and enhanced triggered T cell responses in follicular lymphoma (FL)." (PMID 31195368, 2019).
gastric tumor (3 papers, 2020 to 2023). "Specifically, 70% of gastric tumor tissues demonstrated reduced CD80 expression." (PMID 37765273, 2023). "The highest gene expression levels in the gastric tumor dataset were observed for AJUBA (1.44 × 1014), GPNMB (1.11 × 1014) and CD80 (1.09 × 1014)." (PMID 37765273, 2023). "Previous reports suggest that CD80 exhibits anti-tumor functions and is a co-stimulatory factor in the induction of cytotoxic T lymphocytes (CTL) in the suppression of stomach tumor metastasis 26-28." (PMID 32025206, 2020).
graft versus host disease (3 papers, 2013 to 2021). An immune system disorder that occurs after allogeneic hematopoietic stem cell transplant and is a reaction of donor immune cells against host tissues. "Similarly, in a chronic graft versus host disease (GVHD) model of SLE generated by transfer of splenocytes from 6.C-H2bm12/KhEg mice into BL6 or BL6 miR-21−/−, lack of miR-21 showed a drastic reduction in autoantibody titers, CD40:CD40L and CD28:CD80/86 stimulation signals." (PMID 30322050, 2018).
HIV-1 infection (3 papers, 2016 to 2025). The type species of lentivirus and the etiologic agent of acquired immunodeficiency syndrome (AIDS). "We found an upregulation of pro-inflammatory markers, i.e., HLA-DR, CD38, CD86, and CD80, during early HIV-1 infection stage in several organs, which persisted into the late infection stages." (PMID 39575258, 2024). "Rab11 has been implicated in the deployment of the T cell co-stimulatory molecules CD80 and CD86 from the cell surface of monocytes, during HIV-1 infection." (PMID 27005655, 2016). "Upon HIV-1 infection of MDMs, we also observed a higher level of ISG induction in MDMs from older donors, including IRF5, as well as several known IRF5-responsive genes, such as CXCL16, CCL5, and CD80." (PMID 40493408, 2025).
Hypertension (3 papers, 2019 to 2023). The presence of chronic increased pressure in the systemic arterial system. "When baseline cardiovascular diseases were compared across index classes, a comparatively high proportion of patients treated with anti-CD80/86 agents had hypertension or ischemic heart disease." (PMID 36757417, 2023). "This ENaC-dependent increased formation of IsoLG-adducted proteins in DCs after exposure to high salt correlates with an increase in surface expression of B7 ligands CD80 and CD86 indicating DC maturation and is essential for the pathogenesis of hypertension [16••]." (PMID 32852643, 2020). "Unfortunately, in our study, CTLA-4-dependent modulation of the CD80/CD86-CD28 pathway was not able to prevent the angiotensin II-induced hypertension." (PMID 31147569, 2019).
myocarditis (3 papers, 2017 to 2024). Myocarditis is a condition that is characterized by inflammation of the heart muscle (myocardium). "In more severe cases of myocarditis, treatments such as abatacept (i.e., blocking CD80/86) or alemtuzumab (anti-CD52) can be administered." (PMID 39247203, 2024). "Both CD80 and CD86 arose from gene duplication and have shared functions; however, only CD80 exacerbates myocarditis." (PMID 37175422, 2023). "Myocarditis significantly increases B cell activation and antigen presentation, which was observed alongside increased CD69, CD40, CD80, and MHCII expression 7 dpi." (PMID 37175422, 2023). "The cardiac tissue of infected mice at the acute state of myocarditis (7 days p.i.)revealed significantly increased numbers of CD11b+, CD68+, and CD80+ cells, whereas no increased inflammation was detected 28 days after CVB3 infection." (PMID 28352641, 2017).
nasopharyngeal carcinoma (3 papers, 2007 to 2022). A carcinoma arising from the nasopharyngeal epithelium. "A high-level expression of CD80 and CD86 may result in a high survival benefit of patients with nasopharyngeal carcinoma." (PMID 33092083, 2020). "This study examined the expression of B7-1 (CD80) and B7-2 (CD86) costimulatory molecules along with HLA-DR and the presence of infiltrating lymphocytes and dendritic cells to assess their significance in patients with nasopharyngeal carcinoma (NPC)." (PMID 17524139, 2007).
non-Hodgkin lymphoma (3 papers, 2021 to 2024). Distinct from Hodgkin lymphoma both morphologically and biologically, non-Hodgkin lymphoma (NHL) is characterized by the absence of Reed-Sternberg cells, can occur at any age, and usually presents as a localized or generalized lymphadenopathy associated with fever and weight loss. "In contrast to our results in dogs, in one study of 241 human patients, CD80 was expressed in 43 to 97% on B cell tumors, including diffuse large cell and marginal zone lymphoma, which are common subtypes of B cell tumors in dogs." (PMID 39224452, 2024). "CD80 and CD86 are highly expressed in approximately two-thirds of a cohort of 70 malignant B cell samples from patients with non-Hodgkin lymphoma." (PMID 33868277, 2021).
oral squamous cell carcinoma (3 papers, 2007 to 2021). "Recently, CD80 expression has been demonstrated to be closely associated with decreased tumorigenicity in oral squamous carcinoma, suggesting that inadequate CD80 expression during early oral squamous cell carcinoma formation may contribute to the escape of tumors from the immune system." (PMID 17524139, 2007).
pneumonia (3 papers, 2021 to 2023). An acute, acute and chronic, or chronic inflammation focally or diffusely affecting the lung parenchyma, caused by an infection in one or both of the lungs (by bacteria, viruses, fungi, or mycoplasma.). "In a study by Parker, CD80 and CD86-deficient mice displayed significant reductions in several pro-inflammatory cytokines and significantly improved survival rates in a murine model of pneumonia." (PMID 37004108, 2023).
primary biliary cholangitis (3 papers, 2016 to 2020). Primary biliary cholangitis (PBC) is a chronic and slowly progressive cholestatic liver disease of autoimmune etiology characterized by injury of the intrahepatic bile ducts that may eventually lead to liver failure. "In Japanese cohorts, TNFSF15, POU2AF1, ARHGAP31, TMEM39A, POGLUT1, TIMMDC1, and CD80 were found to be susceptibility loci of primary biliary cholangitis, while SNP rs13720 in CTSZ was strongly associated with jaundice progression." (PMID 33202590, 2020). "Another European cohort including more than 7000 individuals identified 12 new loci related to biliary cirrhosis, among them were STAT4, IL7R, CD80, IKZF3, CXCR5, TNFRSF1A, and NFKB1." (PMID 33202590, 2020).
visceral leishmaniasis (3 papers, 2017 to 2025). A severe form of leishmaniasis characterized by irregular bouts of fever, substantial weight loss, swelling of the spleen and liver, and anemia (which may be serious). "A decreased T lymphocyte activation, possibly caused by a decrease in CD86 and an increase in CD80 expression, is consistent with the findings observed in human visceral leishmaniasis." (PMID 29358935, 2017). "On the contrary, in visceral leishmaniasis, the N-DC hybrids present at disease presentation expressed MHC class II, CD80, and CD86 but were associated with an anergic phenotype." (PMID 40340446, 2025).
Alzheimer disease (2 papers, 2013 to 2021). A progressive, neurodegenerative disease characterized by loss of function and death of nerve cells in several areas of the brain leading to loss of cognitive function such as memory and language. "This network contains the proinflammatory cytokine Il1a, previously associated with Alzheimer’s disease, development and plasticity, immune associated genes (Cd80, Cr2, Cd27, Dapp1) and chemokines (Ccl3, Ccl4, Ccl21)." (PMID 23742273, 2013).
Atherosclerotic lesion (2 papers, 2022). A lesion associated with atherosclerosis, a multifactorial and multipart progressive disease manifested by the focal development within the arterial wall of lesions, that ranges from the development of a fatty streak, plaque progression, and plaque disruption.
atopic dermatitis (2 papers, 2015 to 2024). "However increased CD80 and CD86 are observed in chronically inflamed skin conditions, such as atopic dermatitis." (PMID 25992642, 2015).
biliary tract cancer (2 papers, 2021 to 2024). "A study on biliary tract cancers including CCA reported that strong CD80 expression in tumor tissue was closely associated with resistance to adjuvant chemotherapy." (PMID 34069452, 2021). "The IVW analysis for classical dendritic cells revealed that CD80 on myeloid dendritic cells had an IVW result of (OR=1.09, 95% CI=1.00–1.19, P=0.04), indicating a positive correlation with biliary tract cancer as OR > 1 suggests." (PMID 39050844, 2024).
celiac disease (2 papers, 2019 to 2021). An autoimmune genetic disorder with an unknown pattern of inheritance that primarily affects the digestive tract. "As regards coeliac disease diagnosis above 7 years of age in the case–control analysis, rs653178 (at SH2B3/ATXN2), rs13010713 (at ITGA4/UBE2E3), rs13151961 (at IL2/IL21), rs11712165 (at CD80) and rs10936599 (at MYNN) showed an association." (PMID 33446885, 2021).
chronic asthma (2 papers, 2014 to 2022). An asthma that is characterized by the development of persistent airway inflammation and recurrent attacks of breathlessness and wheezing, which vary in severity and frequency. "Moreover, the HSP70/CD80 DNA vaccine has been found to reduce airway remodeling in chronic asthma via regulating the transcription factors T-bet and GATA-3, which are essential for Th1 and Th2 differentiation." (PMID 36553658, 2022). "However, in an animal model of acute exacerbation M2 macrophages triggered Th2 cytokines in CD4+ T-lymphocytes through the interaction with CD80/CD86, which was not seen in a model of mild chronic asthma." (PMID 24612750, 2014).
chronic obstructive pulmonary disease (2 papers, 2023 to 2025). A chronic and progressive lung disorder characterized by the loss of elasticity of the bronchial tree and the air sacs, destruction of the air sacs wall, thickening of the bronchial wall, and mucous accumulation in the bronchial tree. "In humans, only one study reported MHC Class II and CD80 expression on ILC2 cells as being elevated in patients with acute exacerbation of chronic pulmonary obstructive pulmonary disease (AECOPD)." (PMID 37781372, 2023). "Human moDCs differentiated from monocytes of chronic obstructive pulmonary disease (COPD) patients expressed increased levels of CD80, CD86 and IFN-α as compared with those of healthy individuals." (PMID 41306974, 2025).